PDK1 (pyruvate dehydrogenase kinase 1)
Diseases named in the same sentence as PDK1 in open-access papers (continued):
Sharing a sentence is not in itself a finding about the gene and the disease.
prostate carcinoma (continued). "In this section, we attempted to clarify how cell density affects OXPHOS in prostate cancer cells by examining the mRNA expression levels of two OXPHOS-related genes, synthesis of cytochrome c oxygenase 2 (SCO2) and pyruvate dehydrogenase kinase 1 (PDK1)." (PMID 36919762, 2023). "KDM4A-E2F1 complex regulates metabolism by upregulating pyruvate dehydrogenase kinase 1 (PDK1) and pyruvate dehydrogenase kinase 3 (PDK3), thereby promoting the switch of oxidative phosphorylation to glycolytic metabolism in prostate cancer cells." (PMID 35689245, 2022). "Correlation between clinical and pathological variables and PDK1, PDK2, PDK3 and PDK4 protein expression in prostate cancer." (PMID 35692804, 2022). "Immunohistochemistry (IHC) staining was used to study the expression of PDK1 and SPOP in prostate cancer tissues." (PMID 34353330, 2021). "In echoing this finding, we detected PDK1 expression in prostate cancer patients, and observed that samples of SPOP mutants displayed a relative higher PDK1 expression compared with that of samples harboring intact SPOP." (PMID 34353330, 2021). "In this study we not only reveal the tumor suppressive role of SPOP by targeting PDK1 for degradation and AKT inactivation, but also highlight combating PDK1-AKT pathway as a potent strategy to treat SPOP mutant-driven prostate cancer." (PMID 34353330, 2021). "The inhibition of PDK1/AKT signaling by DMC or OSU treatment represents an important component of DMC/OSU-induced apoptosis in different cancers (e.g., prostate cancer cells, glioblastoma)." (PMID 34356673, 2021). "In this study, we found that PDK1 and PFKFB4 played a role in regulating the proliferation, invasion and migration of prostate cancer cells." (PMID 29029419, 2017). "In this study, shRNA-mediated PDK1 and PFKFB4 ablation in prostate cancer cells should alleviates the aggressive such as cell proliferation, cell migration and invasion." (PMID 29029419, 2017). "First, we investigated the effects of PDK1 and PFKFB4 for prostate cancer cell proliferation using MTT assay." (PMID 29029419, 2017). "Mechanistic studies demonstrate that the overexpression of hsa‐miR‐3916 significantly downregulates the protein expression of pyruvate dehydrogenase kinase 1 (PDK1), thereby attenuating glycolytic metabolism and suppressing the migratory and invasive capacities of prostate cancer (PCa) cells." (PMID 41187909, 2025). "In support of this notion, depletion of endogenous Cullin3 led to an evident increase of endogenous PDK1 in prostate cancer 22Rv1 and DU145 cells, indicating that Cullin3-based E3 ligase could govern PDK1 protein stability." (PMID 34353330, 2021). "Supporting these findings, the PDK1 bona fide readouts such as pRSKSer221 and pAKTThr308 were not representative of the PDK1 inhibition in prostate cancer cells." (PMID 29064423, 2017). "Silencing of PDK1 and PFKFB4 could decrease cell proliferation, inhibit invasion and migration ability of prostate cancer cells." (PMID 29029419, 2017). "In present analysis of PI3K/AKT pathway in DU145/XB130- and LNCap/XB130- cells, XB130 knockdown was accompanied by reduced expression of p-PDK1, thr308, p-C-Raf and upregulation of p-PTEN, which indicates that reducing XB130 deters Akt pathway in prostate cancer as in other cancers." (PMID 27509056, 2016). "Moreover, both in SPOP knockout prostate cancer cells and MEFs, SPOP depletion could enhance PDK1 protein levels coupled with increased AKT phosphorylation in T308." (PMID 34353330, 2021). "Importantly, we further observed that depletion of SPOP with different sgRNAs could significantly elevate endogenous PDK1 protein levels, as well as well-established SPOP substrate Trim24 in prostate cancer cell lines." (PMID 34353330, 2021). "Interestingly, PDK1 RNAi-mediated knockdown does not impair Pten-deleted prostate cancer growth in mice, possibly reflecting mTORC2-mediated activation of AKT, and/or compensatory augmentation of the MAPK cascade." (PMID 32630372, 2020).
non-small cell lung carcinoma (29 papers, 2010 to 2025). A group of at least three distinct histological types of lung cancer, including non-small cell squamous cell carcinoma, adenocarcinoma, and large cell carcinoma. "In contrast, C-CBL has been identified as a significant proto-oncogene in various cancers and linked to the downregulation of PDK1 in EGFR wild-type non-small cell lung cancers, suggesting its potential role in immune responses." (PMID 38272982, 2024). "PDK1 is upregulated in non-small cell lung cancer (NSCLC) cells, andPDK1 silencing inhibits the survival of NSCLC cells via the Hippo-YAP/IRS2 pathway." (PMID 39578715, 2024). "Acquired resistance to osimertinib is driven by PDK1 in preclinical models of non-small cell lung cancer and reveals PDK1 as a potential target for restoring osimertinib sensitivity." (PMID 37169941, 2023). "PDK1 overexpression has been shown to induce proliferation and metastasis through the Warburg effect in non-small cell lung cancer." (PMID 36901698, 2023). "It was reported that miR-145-3p is down-regulated in non-small cell lung cancer, and inhibited cell migration and invasion by targeting PDK1 via the mTOR signaling pathway." (PMID 34350110, 2021). "In non-small cell lung cancer, glutamine shortage leads to the PDK1/Akt axis activation, which in turn promotes metastasis." (PMID 29064423, 2017). "miR-138 inhibited cancer cell growth and tumorigenesis in non-small cell lung cancer and nasopharyngeal cancer by targeting 3-phosphoinositide-dependent protein kinase-1 (PDK1) and CCND1." (PMID 24941171, 2014). "Besides, pyruvate dehydrogenase kinase 1 (PDK1) was demonstrated to be overexpressed in non-small cell lung cancer tissues and promote cell proliferation and migration by modulating aerobic glycolysis." (PMID 36072431, 2022). "However, PDK1 has previously been reported to significantly induce the proliferation of non-small cell lung cancer and retinoblastoma." (PMID 34298795, 2021). "In addition, PDK1 is highly expressed in non-small cell lung cancer (NSCLC), and its overexpression is significantly correlated with poor prognosis in human NSCLC tissues." (PMID 32825675, 2020).
colon carcinoma (28 papers, 2008 to 2025). "Besides, Dai W had revealed that PDK1 deficiency blocked proliferation of colon cancer cells and led to apoptosis." (PMID 34848810, 2021). "In colon cancer models, Wnt signaling directly induces pyruvate dehydrogenase kinase 1 (PDK1) transcription via β-catenin/TCF binding to its promoter." (PMID 41300720, 2025). "Wnt signaling enhances anaerobic glycolysis in colon cancer cells via increased pyruvate dehydrogenase kinase 1 (PDK1) expression." (PMID 37109525, 2023). "We also examined the expression of genes and transcription factors in key metabolic signaling pathways across the subpopulation, the most abundant genes in colon cancer were PDK1, NRF1, MYC, and HIF1A." (PMID 35755820, 2022). "On the other hand, data from breast epithelial cells and colon cancer cells indicate that PI3K/PDK1/AKT signaling promotes YAP activity via LATS-dependent and -independent mechanisms." (PMID 30931304, 2019). "Specifically, it was reported that PDK1 served as a direct downstream target gene of Wnt/β-catenin signaling in colon cancer cells and mediated aerobic glycolysis." (PMID 29764469, 2018). "Recently, activation of canonical Wnt signaling was reported to directly act on aerobic glycolysis and increase vessel formation in colon cancer through the Wnt target gene pyruvate dehydrogenase kinase 1 (PDK1)." (PMID 29599799, 2018). "In colon cancer, this reprogramming is due to direct regulation of pyruvate dehydrogenase kinase 1 (PDK1) gene transcription." (PMID 27729975, 2016). "Our study indicates that STS down-regulates PI3K, AKT, and PDK1 phosphorylation in CT26 colon carcinoma cells." (PMID 25909219, 2015). "Rapamycin and the mTORC1/2 inhibitor Torin increased Akt phosphorylation on the PDK1 site Thr308 in the rapalog resistant HCT116 colon cancer cell line." (PMID 24927123, 2014). "PDK1 is upregulated in several cancers, especially colon cancer." (PMID 28298922, 2017). "Thus, in colon cancer, activation of canonical Wnt signaling directly acts on aerobic glycolysis and increases vessel development via the Wnt target gene PDK1." (PMID 28298922, 2017). "We used this type of analysis in colon cancer cells to discover that Wnt signaling promotes tumor cell preferences for aerobic glycolysis/Warburg metabolism, with the Wnt target gene pyruvate dehydrogenase kinase 1 (PDK1) playing a significant role in this metabolic fate." (PMID 27729975, 2016). "These compounds were evaluated for their antioxidant activity, inhibition of PDK-1 and LDHA, as well as their antiproliferative effects against HCT-116 and LoVo colon carcinoma cell lines." (PMID 40573199, 2025). "In colon cancer, interleukin-1 (IL-1) and TAMs collaborate to activate NF-κB-dependent PDK1/AKT signalling in tumour cells, inactivating glycogen synthase kinase 3 beta (GSK3β), amplifying Wnt signalling, and fostering colon cancer cell proliferation." (PMID 38136392, 2023). "To demonstrate the tumor initiating potential of these cells, we took advantage of the mouse colon cancer cell line MC38, which we transduced with the Pdk1-mCherry reporter to generate MC38-Pdk1-mCherry cells." (PMID 35314684, 2022). "Searching for the distinct molecular mechanism, we identified several contributors to proliferation of LS174T colon cancer cells: PI3K subunits/PTEN, PDK1/AKT, and Src/Raf/Ras/ERK." (PMID 34997428, 2022). "For example, the metabolic enzymes pyruvate dehydrogenase kinase 1 (PDK1) and PCK1 are required for hepatic colonization in animal models of breast and colon cancer, respectively." (PMID 33931119, 2021). "Finally, a positive correlation among the SMURF1 level, PDK1 neddylation, and AKT phosphorylation in colon cancer tissues was found." (PMID 39331402, 2025).
colon carcinoma (continued). "Here, we report a self‐organizing spatial pattern of glycolysis in xenograft colon tumors where pyruvate dehydrogenase kinase (PDK1), a negative regulator of oxidative phosphorylation, is highly active in clusters of cells arranged in a spotted array." (PMID 28183841, 2017).
diabetes (22 papers, 2012 to 2025). "However, upregulation of PDK4 and PDK1 expression has been linked to obesity and diabetes, respectively." (PMID 40868918, 2025). "Finally, our ORM and Morris water maze behavior tests displayed that PDK1 in the hippocampus attenuated hyperglycemia-induced memory loss in mice model of diabetes." (PMID 37935660, 2023). "Our data showed a significant decrease of PDK1 in neurons of the hippocampus in mice models of diabetes." (PMID 37935660, 2023). "The secondary consequences of inhibiting PDK1 include the promotion of diabetes and interference with lipid metabolism and cyclo-oxygenase activity." (PMID 37296860, 2023). "When investigated in adipose tissue in relation to the development of obesity and diabetes, it was found that deleting PDK1 in mice produced insulin resistance and glucose intolerance in adipose cells, typical of diabetes." (PMID 37296860, 2023). "Diabetes (islets) or chronic hyperglycaemia (INS-1 cells) markedly enhanced Pdk1 expression and phosphorylation of PDHe1α." (PMID 36376280, 2022). "For instance, PDK4 is involved in metabolic changes under high-fat diet condition and diabetes, while PDK1 and PDK3 are more likely to contribute to metabolic switch and cell survival under hypoxia." (PMID 31409724, 2019). "In summary, we propose a model where diabetes induces the PDK1 reduction in oocytes, which lowers the phosphorylation level of Serine 232 on PDHE1α and disturbs its enzymatic activity, consequently disrupting the assembly of meiotic apparatus during oocyte maturation." (PMID 34988082, 2021). "The expression of PDK1 was lower in patients with diabetes compared with controls." (PMID 25950482, 2015). "Therefore, in our study, we hypothesized that the increased glucose concentration in diabetes may increase the expression of microRNA375, which may consequently repress the expression of Pdk1 and I3K/Akt pathway, damage EGC survival." (PMID 30140011, 2018). "Previously, it was observed that miR-375 has a role in diabetes, where its mechanism depends on controlling the expression of myotrophin (MTPN) and phosphoinositide-dependent protein kinase-1 (Pdk1) genes." (PMID 36874371, 2022). "Therefore, it is in our best interest into investigating whether ecARNT in diabetes would regulate the production of ROS resulting from the upregulation of OXPHOS via a novel PDK4 dependent pathway or through the same pathway regulated by PDK1 above." (PMID 34179020, 2021). "Also, a single TRDI dose (G4) increased IRS-1, PDK1, and Akt phosphorylation in diabetic mice when compared with the STZ-induced diabetes control group (G2), supporting our in vitro and in vivo findings." (PMID 35883721, 2022). "Additionally, we investigated if TRDI elevated insulin signaling in these mice; IRS-1, PDK-1, and Akt were phosphorylated in the STZ-induced diabetes plus TRDI group (G4)." (PMID 35883721, 2022). "In conclusion, we demonstrate that the PHD-dependent HIF-1 repression induced by high glucose concentrations contributes to excessive production of mitochondrial ROS in diabetes, which is mediated by increased mitochondrial respiration secondary to the inhibition of HIF-1 target gene PDK1." (PMID 35164902, 2022). "Comparison of control and diabetic hearts showed that the expression of PDK-1 was not affected by diabetes or by ROCK inhibitor treatment." (PMID 24466133, 2014). "Unlike the roles of PDK2 and PDK4, the role of PDK1 is underexplored in obesity and diabetes." (PMID 34552205, 2021). "However, the mechanisms that control PDK1 have not been fully explored and this is of great importance as interfering with PDK1 signaling may be useful to treat diseases, including cancer and diabetes." (PMID 22347420, 2012).
osteosarcoma (20 papers, 2021 to 2025). A usually aggressive malignant bone-forming mesenchymal neoplasm, predominantly affecting adolescents and young adults. "By elucidating the role of PDK1 in osteosarcoma, this study provides valuable insights into the metabolic mechanisms underlying osteosarcoma progression and identifies PDK1 as a promising prognostic biomarker and therapeutic target." (PMID 40971960, 2025). "Kaplan–Meier survival analysis showed that high expression of PDK1 was associated with poor prognosis of osteosarcoma.(P < 0.001)." (PMID 40971960, 2025). "High PDK1 expression was found to be significantly associated with reduced survival in osteosarcoma patients, suggesting its value as a prognostic biomarker." (PMID 40971960, 2025). "To predict the function of PDK1, including associated pathways, we performed a positive and negative correlation analysis between PDK1 and other genes in osteosarcoma using LinkedOmic online database, with the detailed PDK1 related genes recorded in S5 Table." (PMID 40971960, 2025). "Our findings reveal that high PDK1 expression is associated with significantly reduced survival in osteosarcoma patients, indicating its potential as a prognostic biomarker." (PMID 40971960, 2025). "Notably, CDKN2A,MDM2, and RB1 also appeared in the PDK1-related gene signature derived from our correlation analysis, further supporting the association between PDK1 and osteosarcoma oncogenic programs." (PMID 40971960, 2025). "Importantly,inhibiting PDK1 can interfere with the cell cycle of osteosarcoma, causing osteosarcoma cells to stagnate in the G2/M phase." (PMID 40971960, 2025). "Nevertheless, pharmacological inhibition of PDK1 significantly reduced lung tumor burden in an experimental metastasis model, suggesting that PDK1 expression in OSCs may contribute to metastasis and the poor prognosis associated with osteosarcoma." (PMID 40730548, 2025). "To further explore the role of PDK1 in osteosarcoma progression, we conducted GO enrichment analysis on PDK1, identifying biological processes such as metabolic processes and cell proliferation." (PMID 40971960, 2025). "In this study, the relationship between PDK1 and the metabolism of osteosarcoma cells and the clinical prognosis of patients were explored through bioinformatics." (PMID 40971960, 2025). "The findings suggest PDK1 as a critical regulator of glycolytic metabolism and a potential therapeutic target in osteosarcoma." (PMID 40971960, 2025). "Our scRNA-seq analysis of clinical osteosarcoma specimens revealed that PDK1 expression was significantly elevated in OSCs from primary tumors, but not in those from metastatic or recurrent samples." (PMID 40730548, 2025). "GSEA found that PDK1 plays an important role in regulating the glucose metabolism of osteosarcoma cells." (PMID 40971960, 2025). "We utilized the GEPIA and UCSCXena databases to analyze PDK1 expression in osteosarcoma and its correlation with patient prognosis." (PMID 40971960, 2025). "High PDK1 expression also predicted poorer overall and metastasis-free survival in patients with osteosarcoma according to the microarray dataset (GSE21257) and was linked to poor prognosis of patients with soft tissue sarcoma (TCGA-SARC)." (PMID 40730548, 2025). "Meanwhile, in this study, we first analyzed the clinical data of osteosarcoma and found that the expression level of PDK1 was negatively correlated with tumor progression and prognosis of osteosarcoma in both the total sample and non-metastatic group samples." (PMID 40971960, 2025).